EDN1 (endothelin 1)
Diseases named in the same sentence as EDN1 in open-access papers (continued):
Sharing a sentence is not in itself a finding about the gene and the disease.
vasculopathy (39 papers, 2006 to 2025). "The endothelin-1 blockade is a potential target and therapeutic strategy in SSc-caused vasculopathy." (PMID 38308348, 2024). "Endothelin-1 (ET-1), a potent vasoconstrictive peptide, is overexpressed and strongly associated with many vasculopathies." (PMID 34070407, 2021). "The important role of endothelin-1 in the development of SSc-associated tissue fibrosis and fibroproliferative vasculopathy has received increasing attention recently." (PMID 24175099, 2013). "TGF-β-induced synthesis of endothelin-1 (ET-1) may utilize one of the Smad-independent pathways to mediate the pro-fibrotic response and vasculopathy that is a hallmark of SSc." (PMID 29353817, 2018). "Endothelin 1 (ET-1; at pixel density 11427 ± 2065.46), a molecule that has been implicated in the development and progression of vascular disorders and usually secreted by endothelial cells upon stimulation by proinflammatory cytokines or hypoxia, could also be detected upon TNFα treatment." (PMID 24195074, 2013). "Conditioned media containing secreted proteins from Snail-tg keratinocytes upregulated vasculopathy-related genes such as Edn1 and Pdfgb, while promoting an endoMT phenotype, as assessed by a collagen contraction assay." (PMID 40540411, 2025). "There are several serological biomarkers that reflect the vasculopathy of the disease: ROS, endothelin 1 (ET‐1), cell adhesion molecules (eg, E‐selectin) and anti‐endothelial antibodies." (PMID 29664231, 2018). "In all forms of PAH, the progressive vasculopathy is a complex with a broad imbalance of vasodilators, such as nitric oxide (NO) and prostacyclin, and vasoconstrictors, such as endothelin-1 (ET-1) and thromboxane A2." (PMID 27886187, 2016). "Endothelin-1, a highly potent vasoconstrictor produced by the endothelial cells, is believed to be a key mediator of the vasculopathy." (PMID 23653656, 2013). "Recruited chronic inflammatory cells secrete transforming TGF-β, CTGF, and other profibrotic growth factors which along with endothelial cell released mediators, such as endothelin-1, enhance the fibroproliferative vasculopathy characteristic of the disease and potentially activate EndMT." (PMID 30283435, 2018). "Unlike COPD, where endothelin-1 predominated, SSc-ILD associations reflected systemic fibrotic remodeling and multi-organ vasculopathy." (PMID 41010963, 2025). "Our previous data suggest that endothelin-1 (ET-1), a potent vasoactive peptide, is increased during ECM and may contribute to the vasculopathy observed during malarial infection." (PMID 27031954, 2016).
cardiac disease (17 papers, 2007 to 2025). "The levels of endothelin-1 and procollagen 1 in these patients were similar to those found in T. cruzi-infected subjects with severe cardiac disease." (PMID 31199841, 2019). "We analyzed PM effect on cytokine levels in 21 individuals with known cardiac disease by pairing 59 repeated-measures of endothelin-1, IL-6 and IL-6 receptor, TNF-α and TNF-α receptors [p55, p75], and MCP-1 to outdoor residence level measures of PM." (PMID 17270049, 2007). "Moreover, we postulated that endothelin-1 and IL-6 levels would be elevated on high air pollution exposure days in individuals with pre-existing heart disease." (PMID 17270049, 2007).
metabolic disorders (11 papers, 2013 to 2025). "IR is also a major mediator which further intensifies the risk of the metabolic disorders such as T2D and CVD as it decreases nitric oxide (NO) and increases endothelin-1 (ET-1) in arterial endothelial cells." (PMID 40650016, 2025). "However, we are not aware of defects in the processing of pre‐proendothelin‐1 to ET‐1 with insulin stimulation or metabolic disease." (PMID 27796268, 2016).
inflammation (9 papers, 2007 to 2025). Aberrant reaction of the microcirculation characterized by movement of fluid and leukocytes from the blood into extravascular tissues. "Age-dependent effects of overexpression of prepro-endothelin-1 or ETB deficiency on pulmonary inflammation and the cardiovascular system were studied in mice." (PMID 35757687, 2022).
neurodegenerative disease (7 papers, 2013 to 2025). A disorder of the central nervous system characterized by gradual and progressive loss of neural tissue and neurologic function. "The elevation of EDN1 in the cerebral cortex in AD is not simply a nonspecific consequence of neurodegenerative disease." (PMID 26452729, 2016).
bacterial infection (5 papers, 2008 to 2017). "Several genes identified through our experimental approach have been linked to roles in host responses to bacterial infection (CCL5, ITLN1), immune modulation (ZFP36, NFKBIA) and damage (EDN1) during PD or during episodes of PD peritonitis." (PMID 28542390, 2017).
cerebral artery (4 papers, 2013 to 2024). "We showed that relaxin-2 (relaxin) exerts a protective effect in lung IR, attributable to decreases in endothelin-1 (ET-1) production, leukocyte recruitment, and free radical generation." (PMID 24098703, 2013).
connective tissue diseases (3 papers, 2023 to 2025). "While not clinically available, antibodies against endothelin 1 (ET-1) and Ang receptor type 1 (AT1R) have been identified in patients with SSc and other connective tissue diseases at a much higher rate than in IPAH, and have been proposed as both predictive and prognostic biomarkers in SSc-PAH." (PMID 38731946, 2024).
hematological diseases (2 papers, 2014 to 2022). "In contrast, endothelin-1 is undetectable in unstimulated B and T lymphocytes or neutrophils and in several cell lines from hematological malignancies." (PMID 24901342, 2014).
movement disorder (2 papers, 2006 to 2021). Neurological conditions resulting in abnormal voluntary or involuntary movement, which may impact the speed, fluency, quality and ease of movement. "The contribution of endothelial derived factors could be crucial; endothelin-1 (ET-1) is a proven potent vasoconstrictive agent that is also believed to affect hyperalgesia, muscle weakness and movement disorders, and oedema." (PMID 17137491, 2006).
brain disorder (1 paper, 2021). A disease affecting the brain or part of the brain. "The production of brain endothelin-1 (ET-1), which increases in brain disorders, is involved in the pathophysiological response of the nervous system." (PMID 33919338, 2021).
heart (1 paper, 2014). "Tacrolimus immunosuppression with resultant reduction of systemic endothelin-1, promotion of microvascular endothelial function, and increment in the mean vessel area over time with positive vascular remodeling have been reported in heart transplant recipients." (PMID 25114905, 2014).
respiratory diseases (1 paper, 2021). "The most common mediators of airway inflammation involved in horse respiratory diseases include histamine, bradykinin, prostaglandins, leukotrienes, platelet factor and endothelin-1." (PMID 34066204, 2021).
EDN1 also shares sentences with these, for which no sentence is quoted: essential hypertension (24 papers); acute myocardial infarction (20); hyperlipidemia (14); renal failure (12); idiopathic pulmonary fibrosis (11); autoimmune disease (9); hypertrophy (9); dementia (8); infectious disease (8); retinopathy (8); anemia (6); renal dysfunction (6); systemic lupus erythematosus (6); thrombosis (6); ulcer (6); cerebrovascular diseases (5); HELLP syndrome (5); neuroblastoma (5); peripheral arterial disease (5); respiratory distress syndrome (5); acute lung injury (4); acute respiratory distress syndrome (4); astrocytoma (4); brain injury (4); cerebral infarction (4); edema (4); exfoliation glaucoma (4); Graves disease (4); hypotension (4); macular edema (4).
A further 314 diseases each share a sentence with EDN1 in 4 papers or fewer.